ZSWIM4 (zinc finger SWIM-type containing 4)
Synonyms: FLJ12221
Tractability: PROTAC: ubiquitination databases record sites on it.
Gene: Protein-coding gene on chromosome 19 (13,795,398 to 13,832,254, forward strand). Ensembl gene ENSG00000132003.
Gene Ontology:
Molecular function: zinc ion binding
Cellular component: Cul2-RING ubiquitin ligase complex
Genetic constraint (gnomAD): Loss-of-function variants: 61 observed, 91.01 expected, observed/expected ratio (o/e) 0.67, 90% interval 0.54 to 0.83. The upper end of that interval is the gene's LOEUF score, 0.83, which puts it in group 3 of 6, group 1 being the genes least tolerant of losing a copy. Missense variants: 1,241 observed, 1,465.3 expected, observed/expected ratio (o/e) 0.85, 90% interval 0.81 to 0.89. Synonymous variants: 633 observed, 635.69 expected, observed/expected ratio (o/e) 1, 90% interval 0.93 to 1.06.
Homologues: Orthologues: dog ZSWIM4 (95% identical), pig ZSWIM4 (95% identical), mouse Zswim4 (92% identical), macaque ZSWIM4 (91% identical), chimpanzee ZSWIM4 (81% identical), tropical clawed frog zswim4 (76% identical), rat Zswim4 (75% identical). Paralogues in human: ZSWIM5 (67% identical), ZSWIM6 (63% identical), ZSWIM8 (30% identical).
Diseases named in the same sentence as ZSWIM4 in open-access papers:
ZSWIM4 is named in the same sentence as 12 diseases in open-access papers, as found by Europe PMC text mining. Sharing a sentence is not in itself a finding about the gene and the disease. The quoted sentences say what the papers report.
epithelial ovarian cancer (3 papers, 2024 to 2025). "ZSWIM4, a gene, is associated with poorer prognosis in epithelial ovarian cancer due to its overexpression in tumor tissues and its correlation with increased recurrence rates." (PMID 41465326, 2025).
breast carcinoma (2 papers, 2024). "In our previous study, we found that ZSWIM4 was an inducible drug resistance gene in breast cancer cells." (PMID 38383406, 2024). "Zinc finger SWIM-type containing 4 (ZSWIM4) induces drug resistance in breast cancer cells." (PMID 38383406, 2024). "Previous research has indicated that ZSWIM4 reduces the sensitivity of breast cancer cells to JAK2 inhibitor, and ZSWIM4 might play a role in the response to vitamin D treatment in colon tissues, although the underlying mechanism is not elucidated yet." (PMID 38951864, 2024). "Increased ZSWIM4 expression is correlated with the high clinical stage of colon adenocarcinoma, and activated transforming growth factor beta (TGF-β) signaling results in the upregulation of ZSWIM4 in breast cancer cells." (PMID 38383406, 2024). "Our previous study showed that ZSWIM4 could mediate resistance to apoptosis induced by a non-receptor-type tyrosine-protein Janus kinase 2 (JAK2) inhibitor by upregulating vitamin D receptor levels in breast cancer cells." (PMID 38383406, 2024).
clear cell carcinoma (1 paper, 2024). "This implies that the TMA results can only suggest that ZSWIM4 expression may be higher in serous carcinoma than in clear cell carcinoma." (PMID 38383406, 2024).
gastrointestinal stromal tumor (1 paper, 2024). "In this study, we aimed to investigate the role of ZSWIM4 in gastrointestinal stromal tumors (GISTs)." (PMID 38951864, 2024).
ovarian clear cell cancer (1 paper, 2024). An invasive malignant neoplasm that arises from the ovary and is characterized by a predominance of clear and hobnail malignant epithelial cells. "To investigate the effect of ZSWIM4 in driving chemotherapy resistance, we selected two cell lines with low expression of this protein, IOSE-80 (human normal ovarian epithelial cells) and ES-2 (human ovarian clear cell carcinoma cells) cells, to establish the ZSWIM4 overexpression models." (PMID 38383406, 2024).
tumor (3 papers, 2024 to 2025). "Therefore, the molecular mechanisms underlying the upregulation of ZSWIM4 in EOC tumor tissues require further investigation." (PMID 38383406, 2024). "Based on public database analysis, strong positive correlations between FOXK1 and ZSWIM4 mRNA levels were observed in OC tumor tissues." (PMID 38383406, 2024). "In this study, we report that ZSWIM4 is highly expressed in EOC tumor tissues and is responsible for chemoresistance in EOC cells." (PMID 38383406, 2024). "In this study, we investigated the role of the zinc finger protein ZSWIM4 in GISTs, and our results suggested that ZSWIM4 serves as a tumor suppressor in GISTs by inhibition of KIT signaling." (PMID 38951864, 2024). "Patient-derived organoid (PDO) models were constructed from EOC tumor tissues with ZSWIM4 expression." (PMID 38383406, 2024). "Subsequently, we performed IHC to verify the overexpression of ZSWIM4 protein using EOC tumor tissues (n = 15) and control tissue samples (n = 15), including 10 paired samples." (PMID 38383406, 2024). "ZSWIM4 was overexpressed in EOC tumor tissues and impaired patient prognoses." (PMID 38383406, 2024). "Additionally, examination of tumor tissues from KITV558A/WT mice and KITV558A/WT/ZSWIM4−/− mice by qRT-PCR and western blot showed that loss of ZSWIM4 expression increases KIT and BMAL1 expression." (PMID 38951864, 2024). "ZSWIM4 was overexpressed in EOC tumor tissues and was relevant to a poor prognosis." (PMID 38383406, 2024). "After 2 weeks of treatment, we found that the knockdown of ZSWIM4 also sensitized EOC cells to CBP in vivo, as indicated by the slower growth curve and reduced tumor weights of subcutaneous tumors among the four groups of mice." (PMID 38383406, 2024). "Notably, ZSWIM4 inhibition showed little impact on EOC cell proliferation, whereas the inhibition of glycine affected the growth of tumor cells, indicating that there is a compensatory mechanism in ZSWIM4-knockdown EOC cells to overcome this damage." (PMID 38383406, 2024). "Taken together, our results suggested a negative feedback loop between KIT and ZSWIM4 in GISTs, where ZSWIM4 serves as a tumor suppressor in GISTs by inhibiting KIT signaling and BMAL1, a key component of the circadian clock pathway." (PMID 38951864, 2024). "ZSWIM4 expression in control and EOC tumor tissues was examined using immunohistochemistry." (PMID 38383406, 2024). "Notably, high ZSWIM4 expression in OC indicated a poor prognosis for the patients administered platinum-based treatment, suggesting that high ZSWIM4 expression in EOC tumor tissues might counter the effect of platinum drugs." (PMID 38383406, 2024).
cancer (1 paper, 2024). A tumor composed of atypical neoplastic, often pleomorphic cells that invade other tissues. "Notably, we found a significant increase of ZSWIM4 expression in relapsed primary cancers and a positive correlation between high ZSWIM4 expression and primary tumor recurrence based on the clinical information." (PMID 38383406, 2024). "Interestingly, 11 of the 15 cancer tissues showed high ZSWIM4 expression, whereas only four of the 15 normal control tissues showed ZSWIM4 expression, indicating the upregulation of ZSWIM4 protein levels in EOC." (PMID 38383406, 2024).
ZSWIM4 also shares sentences with these, for which no sentence is quoted: acute myelogenous leukemia (1 paper); colon adenocarcinoma (1); infection (1); schizophrenia (1); serous carcinoma (1).